DBNDD2 (dysbindin domain containing 2)
Description:
May modulate the activity of casein kinase-1. Inhibits CSNK1D autophosphorylation (in vitro).
Synonyms: CK1BP; C20orf35; HSMNP1
Tractability: No criterion of Open Targets' tractability assessment is met for any kind of drug.
Gene: Protein-coding gene on chromosome 20 (45,405,616 to 45,410,870, forward strand). Ensembl gene ENSG00000244274.
Subcellular location (Human Protein Atlas): Cytosol; Nucleoplasm
Gene Ontology:
Molecular function: protein binding; ATPase binding
Biological process: negative regulation of protein kinase activity; regulation of signal transduction
Cellular component: cytoplasm; endoplasmic reticulum; lysosome
Genetic constraint (gnomAD): Loss-of-function variants: 8 observed, 13.61 expected, observed/expected ratio (o/e) 0.59, 90% interval 0.34 to 1.06. The upper end of that interval is the gene's LOEUF score, 1.06, which puts it in group 4 of 6, group 1 being the genes least tolerant of losing a copy. Missense variants: 194 observed, 204.04 expected, observed/expected ratio (o/e) 0.95, 90% interval 0.85 to 1.07. Synonymous variants: 94 observed, 85.32 expected, observed/expected ratio (o/e) 1.1, 90% interval 0.93 to 1.31.
Homologues: Orthologues: chimpanzee DBNDD2 (98% identical), macaque DBNDD2 (98% identical), dog DBNDD2 (87% identical), guinea pig DBNDD2 (86% identical), rabbit DBNDD2 (86% identical), pig DBNDD2 (86% identical), mouse Dbndd2 (83% identical), zebrafish si:ch211-253b8.5 (38% identical), Caenorhabditis elegans dsbn-1 (12% identical), Drosophila melanogaster Dysb (11% identical). Paralogues in human: DTNBP1 (37% identical), DBNDD1 (21% identical).
Diseases named in the same sentence as DBNDD2 in open-access papers:
DBNDD2 is named in the same sentence as 13 diseases in open-access papers, as found by Europe PMC text mining. Sharing a sentence is not in itself a finding about the gene and the disease. The quoted sentences say what the papers report.
breast carcinoma (1 paper, 2022). "Dysbindin domain-containing protein 2 variant DBNDD2:34 that was upregulated in BRCA1 mutated breast cancer was found downregulated in the AKT1 silenced sample compared to control (siNoN)." (PMID 35892586, 2022).
liver cancer (1 paper, 2023). An epithelial or non-epithelial malignant neoplasm that arises from the liver. "While expression of DBNDD2 messenger (m) RNA was lower in all cancer types, expression of the DBNDD1 gene was significantly higher in numerous tumor types, including PCa, lung cancer, and liver cancer, among others." (PMID 37569304, 2023).
Parkinson disease (1 paper, 2020). A progressive degenerative disorder of the central nervous system characterized by loss of dopamine producing neurons in the substantia nigra and the presence of Lewy bodies in the substantia nigra and locus coeruleus. "The genes that directly interact with PLLP are involved in cell-to-cell communication and neurological-related diseases, such as the completion and maintenance of myelin sheath (MOG), the ion transporter (SLC31A2) (Schweigel-Röntgen, 2014), and Parkinson’s disease (DBNDD2)." (PMID 33304381, 2020).
prostate tumor (1 paper, 2023). "We visualized multiple genomic alteration events of the DBNDD1, DBNDD2, and DTNBP1 genes across a set of prostate tumor samples using OncoPrint using a query for alterations." (PMID 37569304, 2023). "Interestingly, we found that only DBNDD1 gene expression in the dysbindin protein family was substantially elevated in prostate tumor samples, whereas DTNBP1 and DBNDD2 gene expressions were not." (PMID 37569304, 2023).
cancer (2 papers, 2022 to 2023). A tumor composed of atypical neoplastic, often pleomorphic cells that invade other tissues. "We performed a pan-cancer analysis with representative genes encoding dysbindin-1, dysbindin-2, and dysbindin-3, including the DTNBP1, DBNDD2, and DBNDD1 genes, respectively." (PMID 37569304, 2023). "Splice variants related to four genes (DBNDD2, DAP, ITPK1, and ROGDI) previously reported upregulated in breast/other human cancers were found downregulated in AKT1 silenced samples compared to control (siNoN)." (PMID 35892586, 2022).
DBNDD2 also shares sentences with these, for which no sentence is quoted: tumor (2 papers); Alzheimer disease (1); colorectal cancer (1); lung carcinoma (1); neurodegenerative disease (1); non-alcoholic fatty liver disease (1); Stroke (1); α-synucleinopathies (1).